STAT3 (signal transducer and activator of transcription 3)
Diseases named in the same sentence as STAT3 in open-access papers (continued):
Sharing a sentence is not in itself a finding about the gene and the disease.
Autoimmunity (continued). "The signal transducer and activator of transcription 3 (STAT3) gain-of-function (GOF) syndrome (STAT3-GOF) is an autosomal dominant disease characterized by complex immune dysregulation, including lymphoproliferation and autoimmunity." (PMID 39247195, 2024). "STAT3, which is an IL-6 mediating transcription factor, has an essential influence on the differentiation and expansion of TH17 cells, a cell population known to induce autoimmunity when overactivated." (PMID 37140667, 2023). "In the context of rare diseases, up-to-date knowledge of all phenotypes, whether immunodeficiency, autoimmunity, or both, is essential to enable effective differential diagnosis (e.g., as in SLE-like phenotype in STAT3 DN)." (PMID 37140667, 2023). "In addition to orchestrating the molecular signaling of Th17 development, STAT3 may also inhibit Foxp3 transcription via blocking the binding of pSmad3 to a transcriptional enhancer of Foxp3 promoter, shifting Th17:Treg balance toward Th17 cells and favoring the development of autoimmunity." (PMID 33411696, 2021). "It has been hypothesized that this inverse correlation between STAT3 and STAT5 could serve as a regulator of autoimmunity, given that both factors respond to the same cytokines." (PMID 31569642, 2019). "Based on these findings, we propose that while Act1 is a necessary signaling molecule for IL-17 signaling, Act1 serves as a negative regulator to modulate Th17-B cell interaction via its impact on IL-23/IL-21/STAT3 axis and CD40, thereby controlling autoimmunity." (PMID 30013031, 2018). "It is attractive to speculate that the suppressive role of STAT3 and STAT6 is important to prevent NK-cell overshoots and autoimmunity." (PMID 28149296, 2016). "Immune responses and autoimmunity are tightly controlled via expression of immunosuppressive/immunoregulatory molecules such as CTLA-4, PD-1/PD-L1, and BTLA that, in turn, are regulated via activation of transcription factors NFAT, NF-κB, STAT3 or STAT4." (PMID 26246474, 2015). "Thus, mice that lack STAT-3 in CD4+ T cells are unable to generate Th17 cells and are resistant to animal models of autoimmunity." (PMID 25374443, 2014). "A comprehensive comparison in terms of demographic, clinical, and immunological features was performed between patients with and without autoimmunity and also among four mutation groups with the most registered cases including ATM, STAT3 (AD-LOF), DNMT3B/ZBTB24, and WAS mutations." (PMID 36544766, 2022). "Aberrant activation of STAT3 due to a gain of functionality might lead to an imbalance of TLR7 and TLR9 response through accelerating integrin signaling pathway, further affecting the development of autoimmunity." (PMID 35345674, 2022). "Moreover, STAT3 is a central component of several lymphocyte signaling pathways raising the question, whether the mutant CD8+ T cell clones play a role in autoimmunity." (PMID 36441748, 2022). "Herein, we report that depletion of Optn in mice by CD11c-Cre promotes JAK2-STAT3 phosphorylation and the forming of IL-10/JAK2/STAT3/IL-10 positive feedback loop, thus impairing DC maturation and the priming of CD4+ T cells to prevent the development of autoimmunity in mice." (PMID 34707127, 2021). "The complex role of IL-6 and STAT3 in both inflammation and autoimmunity could explain the lack of effect." (PMID 33897686, 2021). "STAT3 gain-of-function (GOF) mutations can be responsible for an incomplete phenotype mainly characterized by hematological autoimmunity, even in the absence of other organ autoimmunity, growth impairment, or severe infections." (PMID 33519826, 2021). "When STAT3 is genetically deleted in CD4+ T cells, neither naturally occurring Th17 cells nor Th17-dependent autoimmunity occurs." (PMID 36033859, 2022). "However, TH17 cell expansion has not been shown in the majority of STAT3 GOF patients, suggesting other possible mechanisms related to autoimmunity." (PMID 33442967, 2021).
viral infection (128 papers, 2013 to 2026). "In recent years, the association between STAT3 and viral infections has increasingly become a research focus." (PMID 41488475, 2025). "The precise mechanism underlying the role of STAT3 in viral infection and pathogenicity remains to be further elucidated." (PMID 41488475, 2025). "DC-SIGN present on DC surface has been implicated in activating the STAT3 pathway during viral infection." (PMID 35967323, 2022). "In contrast, here, we demonstrated that C. trachomatis causes inactivation of STAT3, which is observed in limited viral infections such as severe acute respiratory syndrome (SARS) coronavirus and human papillomavirus type 6 or type 11 (51, –, 53)." (PMID 33785629, 2021). "IL-27 strongly induced STAT1-dependent pathways and weakly induced STAT3-dependent pathways implicated in flaring up the viral infection and HCC progression in liver viral infection, suggesting the probable use of IL-27 as a safe treatment in viral hepatitis." (PMID 33381596, 2020). "In vitro and in response to viral infection, STAT3-deficient T cells have a defect in Tfh differentiation, whereas humans with STAT3 dominant-negative mutations have compromised Tfh development." (PMID 32634740, 2020). "Given the diversity of STAT3 functions, many viral infections are associated with the STAT3 signaling." (PMID 32201498, 2018). "The available data imply a correlation between serine mono-phosphorylation of STATs (STAT1 and STAT3) and the proinflammatory response caused by virus infection." (PMID 29312301, 2017). "Activation of the JAK2/STAT3 pathway is associated with inflammation, and inflammation subsequent to viral infection is one factor that initiates and promotes the development of cancer." (PMID 26219895, 2016). "While STAT3 role has been reasonably well characterized in the pathogenesis of oncogenic viruses and viruses causing liver pathology, its role in many other viral infections is less well understood." (PMID 26199948, 2015). "As expected, STAT3 activation was associated with a reduction in type 1 interferon signaling in response to the viral infection." (PMID 23936533, 2013). "One of the immunosuppressive actions of STAT3 in response to viral infections is linked to down-regulation of type 1 interferon signaling." (PMID 23936533, 2013). "According to a recent study, patients with STAT3 mutation presented with more viral infections." (PMID 37371627, 2023). "This defect due to bi-allelic mutations in DOCK8 gene is characterized by distinctive clinical features including severe viral infections, neurological complications, increased risk of malignancies, autoimmunity in addition to the clinical triad observed in STAT3 deficiency." (PMID 36703986, 2022). "Interestingly, the following virus infection abrogates the inhibitory effects of β-blocker on STAT3, causing a drastically increased expression of STAT3/p-STAT3 along with a decrease of PKR/p-PKR." (PMID 34544479, 2021). "The regulation role of STAT3 in our study implies a potential mechanism of the host to protect the CNS from injuries caused by either overactive antiviral response or inflammation during viral infection." (PMID 31575039, 2019). "Finally, we discuss the evolution of the suppressive activity of STAT3 and the therapeutic potential of STAT3 inhibitors in host defense against viral infections and IFN-I-associated diseases." (PMID 31293595, 2019). "However, the role of STAT3 in viral infection is complicated, and various viruses cause differences in the host cell STAT3 activation." (PMID 32201498, 2018). "Therefore, it is also notable that available data implies a correlation between viral-induced serine monophosphorylation of STATs (STAT1 and STAT3) and pro-inflammatory responses caused by virus infection." (PMID 29662014, 2018). "Considering the numerous mechanisms and associations among miRNA, virus infection and STAT3, it possible that certain miRNAs may interact with STAT3 and VZV replication." (PMID 24940427, 2014).
viral infection (continued). "Why HPV oncoproteins or other pathogenic viral infections activate and sustain STAT3 signaling is still unknown." (PMID 25539644, 2014). "Interestingly, IL6/STAT3 signaling is a unique and highly pleiotropic pathway that is evolutionarily conserved and is implicated in both temperature-induced immune responses and virus infection." (PMID 37099596, 2023). "We further examined the relationship between ASS1 expression and STAT3 signaling in the context of viral infection." (PMID 42037409, 2026). "Beyond its canonical transcriptional functions, STAT3 also exhibits phosphorylation-independent activities in cellular respiration, metabolism, autophagy, and viral infection." (PMID 41488475, 2025). "The transcription factor STAT3 is integral to the immune response during viral infections, while long non-coding RNAs (lncRNAs) are actively implicated in the modulation of viral pathogenesis." (PMID 41208976, 2025). "In the case of hMPV, either viral infection or transfection with the hMPV small hydrophobic (SH) protein blocks IL-6-mediated STAT3 activation, thereby promoting hMPV replication." (PMID 41488475, 2025). "For instance, knocking down STAT3 enhanced replication of influenza and vaccinia viruses, highlighting the crucial role of STAT3 in controlling these viral infections." (PMID 40143362, 2025). "The ability of C315R to upregulate IL-6 expression and enhance STAT3 phosphorylation aligns with previous studies on other viral infections." (PMID 40143240, 2025). "It is widely acknowledged that during viral infection, the phosphorylation of STAT3, which is triggered by upstream activators such as interleukin-6 (IL-6), can exert an effective inhibitory effect on viral invasion." (PMID 41488475, 2025). "Several crucial regulators of PD-L1 transcription, such as STAT3 and NF-κB, are activated during viral infection." (PMID 40920828, 2025). "This has been the frequently used approach to study the nuclear-cytoplasmic trafficking of STAT3 and other STATs under various conditions, including viral infection." (PMID 39861822, 2024). "TLR-3 and TLR-7 closely interact with STAT-3, which is crucial for regulating cytokine-mediated responses, such as IL-6 to combat viral infections." (PMID 39281683, 2024). "One of the mechanisms proposed to explain the lymphopenia in severe virus infections is the overproduction of IL‐6 driving the activation of the STAT3 pathway, leading to impaired lymphopoiesis by directly affecting hematopoietic stem cells." (PMID 38115705, 2023). "Numerous investigations through blockage or inhibition of key components of IL6/STAT3 signaling have proven the importance of IL6/STAT3 signaling in virus infection." (PMID 37099596, 2023). "Various stimuli, including viral infection and inflammatory cytokines, activate the NF-κB and STAT3 signaling pathways." (PMID 36851532, 2023). "Among them, IL6/STAT3 signaling, an intrinsic antiviral and pro-inflammatory pathway, has been suggested to contribute to several viral disease progression." (PMID 37099596, 2023). "For all therapies, the risk of adverse events must be considered, such as increased incidence of viral infections in STAT1 GOF during JAK inhibitor use or fatal outcomes in HSCT of STAT3 GOF patients." (PMID 37140667, 2023). "It is known that STAT3 exhibits a proviral function in several viral infections, whereas STAT3 has an antiviral function in other viral infections." (PMID 37378295, 2023). "At the same time, STAT3 was also focused due to its distinct roles in regulating host immune responses and several viral diseases." (PMID 37378295, 2023). "Following viral infection, these circumstances would result in a greater functional STAT3:STAT1 ratio." (PMID 36111104, 2022). "We previously demonstrated that forced SOCS3 expression completely suppressed gp130-mediated STAT3 activation and survival of cardiomyocytes, and that the hearts of SOCS3 transgenic mice exhibited markedly increased susceptibility to viral infection." (PMID 34292971, 2021).
viral infection (continued). "It would be interesting to elucidate how different viruses exploit different axis of the STAT3 signaling to affect viral infections." (PMID 33529218, 2021). "STAT3 becomes hyperactivated or inactivated in viral disease, exhibiting a tightly regulated STAT3 function." (PMID 34071096, 2021). "Studies have shown that STAT6 and STAT3 can be differentially regulated, according to the state of viral infection/vaccination." (PMID 31974500, 2020). "Further investigation showed that SOCS3 promoted virus infection by inhibiting interferon-induced STAT3 phosphorylation." (PMID 32149091, 2020). "We found that viral infection increased the phosphorylation of STAT3 and to a lesser extent of STAT6, molecules activated in M2 polarised macrophages." (PMID 32418990, 2020). "As expected, there was no significant change in MCP-1 expression in both epithelial cell lines indicating an inhibitory effect on STAT3 Tyr705 phosphorylation by virus infection." (PMID 33284859, 2020). "The transcriptional activity of STAT3 is influenced by viral infection and is relevant to the antiapoptotic activity of cells, and MAPK is reported to promote both cell death and survival." (PMID 33224256, 2020). "We infected mice primary astrocytes with EV71 and observed that viral infection induced phosphorylation of STAT3 at both Tyr705 (pSTAT3705) and Ser727 (pSTAT3727) sites, as detected by antibodies specific for each phosphorylation site." (PMID 31575039, 2019). "During periods of bacterial and viral infection, STAT3 creates an inflammatory microenvironment that induces carcinogenesis." (PMID 31892232, 2019). "Some of the viral infections were facilitated by STAT3 since specific inhibitors or siRNAs of STAT3 repressed viral replication." (PMID 31575039, 2019). "As a multifunctional molecule, STAT3 takes part in the regulations of various biological processes including the type I IFN response which is critical for the host defense during viral infection." (PMID 31575039, 2019). "Our data expanded the current understanding on the novel roles of STAT3 in regulating the type I IFN response during viral infection." (PMID 31575039, 2019). "Blockade of IFN-I signaling rescues the defect in LCMV-infected mice, suggesting a requirement of STAT3 for Tfh cell and a fine balance in signaling pathways following acute viral infection." (PMID 31293595, 2019). "This STAT3-induced negative regulation of type I IFN response has been shown in mice models where a STAT3 KO resulted in an increased IFN type I production upon viral infection." (PMID 30984137, 2019). "Factors involving inflammatory cytokines, growth factors and virus infection have been shown to activate hepatic STAT3 signaling." (PMID 31771617, 2019). "Several studies showed that STAT3 affects many kinds of viral infections and pathogeneses, including those of HBV, HCV, varicella zoster virus (VZV), and severe acute respiratory syndrome coronavirus (SARS-CoV)." (PMID 32201498, 2018). "Whatever the effect of STAT1 and STAT3 heterodimers on viral infection, either proviral or antiviral, it provides another layer of potential manipulation for viral gene products that warrants further research." (PMID 29543893, 2018). "STAT3 exhibits a proviral function in several viral infections, including those of HBV, HCV, HSV-1, varicella zoster virus, human CMV and measles virus." (PMID 32201498, 2018). "This review summarizes the roles of STAT3 in viral infection and pathogenesis, and briefly discusses the molecular mechanisms involved in these processes." (PMID 32201498, 2018). "STAT3 dependencies of viruses put a spotlight on the diverse role of signal transduction during viral infections and represent a target for potential antiviral strategies." (PMID 29543893, 2018).
viral infection (continued). "The present review summarizes the roles of STAT3 in these viral infections and pathogeneses, and simply discusses the molecular mechanisms by which STAT3 functions, specifically in the virus life cycles and related disease development." (PMID 32201498, 2018). "Recently, it was shown that type I IFN acts as a repressor of signal transducer and activator of transcription 3 (STAT3), thereby limiting Tfh differentiation in a virus infection model." (PMID 27580796, 2016). "Meanwhile, other authors reported a positive relationship between eosinophil infiltration and STAT3 in nasal polyp or bronchial epithelial damage by virus infection." (PMID 26047496, 2015). "STAT3 role has been well characterized in the pathogenesis of viral infections resulting in liver disease in humans." (PMID 26199948, 2015). "STAT3 is either positively or negatively regulated in a range of viral infections depending on the type of virus involved." (PMID 26199948, 2015). "STAT3 is also known to promote host defense against virus infections and play a protective role in regulating virus mediated proinflammation." (PMID 26199948, 2015). "HPAI-H5N1 virus infection results in STAT3 inhibition and elevated proinflammatory response in chicken cells." (PMID 26199948, 2015). "Complementary in vitro and in vivo experiments are therefore essential to better understand the seemingly contradictory role of STAT3 in viral infections." (PMID 26199948, 2015). "This review summarized the currently known functions of STAT3 in the regulation of viral replication and pathogenesis of viral infections." (PMID 26199948, 2015). "The role of STAT3 in virus replication appears to be complex, as it appears to function as a proviral factor in some viral infections and antiviral factor in others." (PMID 26199948, 2015). "In duck cells, expression of IFNAR1, PIAS2 and STAT-3 was up-regulated by LPAI H2N3 or H5N1-tyEng91 virus infection." (PMID 25431115, 2014). "The effect of the KerraTM and KSTM treatments upregulating IL6 and STAT3 may indicate their role in enhancing immunity to prevent or clear viral infection." (PMID 40733507, 2025). "Viral infection-related pathways, such as Kaposi sarcoma-associated herpesvirus infection (hsa05167; FE = 58.97) and human cytomegalovirus infection (hsa05163; FE = 40.86), were enriched with MTOR, NFκβ1, STAT3, and CASP3." (PMID 41011481, 2025). "In response to viral infections, STAT3 can be activated or inhibited." (PMID 41208976, 2025). "Furthermore, the excessive activation of STAT3 induced by viral infection directly promotes viral replication." (PMID 41488475, 2025). "Anti-inflammatory action of CRY may be attributed to the regulation of signaling cascades such as NF-κB and STAT3, which is frequently activated during viral infections and has been previously shown to be modulated by CRY in other pathological contexts." (PMID 41305456, 2025). "Notably, STAT3 exhibits dual regulatory roles in the context of viral infections, exerting both pro-viral and anti-viral effects depending on the specific viral species and host micro-environment." (PMID 41488475, 2025). "Importantly, this finding aligns with emerging evidence that STAT3 negatively modulates type I IFN-mediated responses across diverse viral infection models, underscoring the evolutionary conservation of STAT3 hijacking as a viral immune escape strategy." (PMID 41488475, 2025). "Importantly, the antiviral efficacy of STAT3 is influenced by multiple factors, including viral titer, host cell type, and the phosphorylation status of STAT3, which highlights its context-dependent role during viral infections." (PMID 41488475, 2025). "However, little information is available about interaction between STAT3 and lncRNAs during viral infection." (PMID 41208976, 2025).